NEUROD1 (neuronal differentiation 1)
Diseases named in the same sentence as NEUROD1 in open-access papers (continued):
Sharing a sentence is not in itself a finding about the gene and the disease.
Stroke (continued). "Taken together, these findings reveal that ectopic expression of Neurod1 is sufficient to improve functional outcomes following stroke as early as 3 weeks post-transduction and maintain recovery to at least 8 weeks post-intervention." (PMID 38540276, 2024). "Through local NeuroD1-based gene therapy, our earlier works on stroke succeeded in increasing the neuron number after endothelin-1 induced focal stroke in mice and rhesus monkeys." (PMID 38270116, 2023). "In the GFP control group, approximately 30% of the mice died in the first week after stroke onset, while the mortality rate in the NeuroD1-treated mice decreased to 4.5%, and only one out of twenty-two mice died from ischemic stroke." (PMID 38270116, 2023). "For NeuroD1 group, the immune-histochemistry results revealed that NeuroD1 was highly expressed in neurons two months after stroke." (PMID 38270116, 2023). "Western blot analysis of the ipsilateral cortical tissue at 7 days post stroke also revealed that ZO-1 expression was significantly increased after NeuroD1 treatment compared to the GFP control group." (PMID 38270116, 2023). "We therefore investigated the effect of the intravenous delivery of NeuroD1 on neuroinflammation after stroke." (PMID 38270116, 2023). "We extracted total mRNA from the stroke infarct cortex (7 dpi, 3 replicates for both the NeuroD1 and control groups) and conducted RNA-seq analysis." (PMID 38270116, 2023). "A separate study using AAV to introduce NeuroD1 under the GFAP promoter ten days post-stroke revealed successful reprogramming of astrocytes into functional neurons with significant improvement in both motor and cognitive functions two months post-treatment." (PMID 36289861, 2022). "Meanwhile, a series of behavioral experiments have also confirmed that after receiving NeuroD1-mediated gene therapy, the motor and cognitive functions of stroke animal models were also significantly improved." (PMID 35663583, 2022). "The master neuronal transcription factor NeuroD1 can directly reprogram astrocytes into induced neurons (iNeurons) after stroke." (PMID 33841125, 2021). "Our current study in NHP stroke model, together with our recent rodent stroke study, shows a consistent finding that NeuroD1-based gene therapy can regenerate a large number of new neurons in the adult mammalian brains." (PMID 33224952, 2020). "In our current study, we have tested NeuroD1-mediated neuronal conversion at three different time windows: 10 days post stroke (3 monkeys); 21 days post stroke (10 monkeys); and 30 days post stroke (3 monkeys)." (PMID 33224952, 2020). "Recently, we have further demonstrated in a mouse stroke model that NeuroD1-based gene therapy can successfully convert reactive astrocytes into functional neurons and promote functional recovery." (PMID 33224952, 2020). "In vivo enforcement of transcriptional factors (Ascl1, Sox2 and NeuroD1) successfully induced ectopic neuronal cells in the ipsilateral cerebral cortex and lateral striatum of the post-stroke mice brain." (PMID 31358888, 2019). "Taken together, the present study successfully achieved, for the first time, in vivo direct reprogramming by enforced transcriptional factors (Ascl1, Sox2 and NeuroD1) in the post-stroke mouse brain." (PMID 31358888, 2019). "We investigated the impact of ectopic Neurod1 expression on post-stroke recovery." (PMID 38540276, 2024). "We designed a strategy to deliver Neurod1 to GFAP+ cells in the stroke-injured cortex." (PMID 38540276, 2024). "Notably, there was a significant decrease in the relative fraction of XFP+GFAP-NeuN- cells at PSD63 in Neurod1-injected mice when compared to Cre controls (stroke/Cre_63d, 19.0 ± 2.7 vs. stroke/Neurod1_63d, 11.1 ± 1.5; p = 0.022)." (PMID 38540276, 2024). "We next examined the ectopic expression of Neurod1 over time in the stroke-injured brain." (PMID 38540276, 2024).
Stroke (continued). "The newly developed NeuroD1-based intravenous gene therapy provides a novel path toward efficient systemic vascular repair, neuroprotection, and neuron regeneration, thus holding significant potenial for stroke recovery." (PMID 38270116, 2023). "Compared to the transgene over-expression before stroke induction, NeuroD1 treatment administered post-stroke may be clinically more relevant." (PMID 38270116, 2023). "In summary, this novel gene therapy mediated by NeuroD1 can produce new effective neurons in patients within 10–30 days of stroke, which may provide stroke patients with a wider treatment time window, thus solving an urgent clinical problem." (PMID 35663583, 2022). "In vivo enforcement of transcriptional factors, such as NEUROD1, successfully induced ectopic neuronal cells in the ipsilateral cerebral cortex and lateral striatum of the post-stroke mice brain and worked as inducers to convert somatic cells into neuronal cells." (PMID 34251509, 2021). "Interestingly, similar to our recent observations made in mouse stroke studies, we also observed significant protection of interneurons after NeuroD1 treatment in monkey stroke model." (PMID 33224952, 2020). "For example, the single neural transcription factor NeuroD1-based gene therapy can successfully reprogram astrocytes into functional neurons in AD mouse brains, damaged spinal cord, and stroke mouse brains, as well as promote functional recovery in a mouse stroke model." (PMID 34124038, 2021). "Different from the published stroke studies of Chen and colleagues, we chose a different AAV serotype to deliver Neurod1 based on reports suggesting enhanced astrocyte targeting with AAV5." (PMID 38540276, 2024). "We have recently developed NeuroD1 AAV-based neuroregenerative gene therapy to treat various neurological disorders, including stroke, Huntington's disease, traumatic brain injury, and spinal cord injury." (PMID 38270116, 2023). "More importantly, following the alteration of endothelial gene expression by NeuroD1, the injured brain cell tropism of AAV-PHP.eB was restored, enabling NeuroD1 to further promote stroke recovery through modulating CNS cell’s function." (PMID 38270116, 2023). "Given the effect of NeuroD1 on the function of BBB, this novel method has great potential to reduce side effects, such as reperfusion injuries post-stroke." (PMID 38270116, 2023). "Further, our studies did not reveal a difference in the lesion volume in our stroke-injured mice that received Neurod1, which was significantly reduced following Neurod1 expression in the previous work." (PMID 38540276, 2024). "In the stroke-injured mice, there were significantly more XFP+ neurons in Neurod1 (2.78 ± 0.7% and 20.2 ± 3.1%, at day 21 and day 56, respectively) compared to Cre-injected brains (0.47 ± 0.26% and 4.67 ± 0.91%, at day 21 and day 56, respectively) (p = 0.031 for day 28 and p < 0.0001 for day 56)." (PMID 38540276, 2024). "We then performed immunostaining for Ki67 to examine proliferative microglial cells after stroke and found a large number of Ki67+ microglial cells in the GFP group, but in the NeuroD1 group, the number of proliferative microglial cells was significantly decreased." (PMID 38270116, 2023). "PACAP also upregulated the brain expression of 15 genes not affected by stroke such as NEUROD1 or BDNF but known to promote synaptic plasticity and which contribute to improve functional recovery." (PMID 33551991, 2020). "In our study, EA could promote neurogenesis after stroke and increase the number of DCX+/NeuroD1+ colocalization in the SVZ." (PMID 32792909, 2020). "To investigate the NeuroD1 treatment effect, we performed a series of immunostaining including NeuN, GFAP, and Iba1 to understand the overall neuronal and glial morphology in the stroke areas." (PMID 33224952, 2020).
Stroke (continued). "Moreover, NeuroD1-based intravenous gene therapy after MCAO protected BBB integrity, attenuated neuroinflammation, increased neuronal density, enhanced the survival rate after stroke, and improved behavioral performance." (PMID 38270116, 2023).
Hyperglycemia (14 papers, 2011 to 2025). An increased concentration of glucose in the blood. "Heterozygous NEUROD1 mutations can disrupt insulin synthesis, impair endocrine pancreas cell maturation, and lead to hyperglycemia (MODY6)." (PMID 39264012, 2024). "A neurogenic differentiation factor 1 (NEUROD1) gene mutation causes beta-cells dysfunction, inadequate insulin secretion, and hyperglycaemia (MODY 6)." (PMID 34654408, 2021). "In mice, loss of Gpd2 is associated with decreased insulin secretion; loss of Neurod1 is associated with hyperglycemia; loss of Mapk8ip1 is associated with abnormal gluconeogenesis and increased insulin sensitivity." (PMID 31776723, 2019). "NEUROD1 is also involved in beta cell dysfunction during chronic hyperglycemia through two mechanisms." (PMID 38274107, 2023). "The total H3 also showed a subtle decrease at E18.5 consistent with what was observed at E14.5; however, at E16.5, an opposite trend was observed where H3 levels showed a modest increase in hyperglycemia on all promoters analyzed except Neurod1." (PMID 35470239, 2022). "The combined expression of NeuroD1 and Btc was found to ameliorate hyperglycaemia in an STZ model with the combination outperforming NeuroD1 or Btc alone." (PMID 33666218, 2021). "However transplantation into streptozotocin-treated mice resulted in further differentiation, including induction of Beta2/NeuroD1 and reduction of hyperglycemia." (PMID 22007286, 2011).
medulloblastoma (14 papers, 2014 to 2025). A malignant, invasive embryonal neoplasm arising from the cerebellum. "Furthermore, a recent report shows that elevated levels of Neurod1 expression are sufficient to drive medulloblastoma cells into granule cell differentiation, which demonstrates that Neurod1 overrides oncogenic mutations present in medulloblastoma cells." (PMID 34177462, 2021). "In tumors, NeuroD1 has demonstrated ability to induce the transdifferentiation of medulloblastoma cells into mature neurons." (PMID 41225636, 2025). "While previous studies have established that NeuroD1 expression in medulloblastoma is epigenetically regulated, our research uncovers a distinct regulatory mechanism in pancreatic cancer, differing from that observed in neurogenic tumors." (PMID 41225636, 2025). "NeuroD1 was regarded as a promising inducing differentiation factor and therapeutic target for the treatment of medulloblastoma." (PMID 41225636, 2025). "CDK8 stands out as a top dependency, similar to OTX2, Neurog1, and Neurod1, well-established genes that sustain stemness and drive proliferation in medulloblastoma 34–37." (PMID 39574899, 2024). "In tumors, NeuroD1 promotes the differentiation of medulloblastoma cells into mature neurons." (PMID 41225636, 2025). "In a study employing a similar co-culture approach with medulloblastoma cell lines and cerebral organoids, NEUROD1—a key molecular determinant of granule cell identity—was expressed only in the co-culture, which represents a more physiological condition, but not in cell lines or tumor spheres alone." (PMID 40917877, 2025). "Our previous research has demonstrated that the expression of NeuroD1 in medulloblastoma could be regulated by epigenetic mechanisms." (PMID 41225636, 2025). "Neurod1 negatively regulates Atoh1 expression during cerebellum, and gut proliferation and manipulating Neurod1 expression that may help to counteract Medulloblastoma." (PMID 37108158, 2023). "Similarly, in medulloblastoma, NeuroD1 promotes medulloblastoma cells to acquire mature neuronal characteristics, again through activating neuron-specific gene expression programs, ultimately leading to the loss of their tumor-initiating and proliferative capacities." (PMID 41225636, 2025). "Overexpression of SNAIL promotes epithelial-mesenchymal transition and thereby drives cancer metastasis, whereas ectopic expression of NEUROD1 and HNF4 is shown to reduce the progression of medulloblastoma and prostate cancer." (PMID 37798384, 2023). "With this in mind, we assessed key transiently activated neural transcription factors (MATH1, NHLH1), and other temporally activated genes (NEUROD1, NHLH2, NFIB, LPPR4, DPYSL3, NEUROD2) expressed throughout granule neuron differentiation, in the medulloblastoma subgroups." (PMID 25412507, 2014). "Activity of the several NEUROG/NEUROD pioneer factors, which are unable to bind to methylated DNA, was compromised via the suppressed expression or DNA hypermethylation of their target sites, which was also experimentally validated for NEUROD1 in medulloblastomas and AT/RT samples." (PMID 38499326, 2024).
neuroblastoma (12 papers, 2014 to 2026). Neuroblastoma (NB) is the most common solid, extracranial childhood tumor. "First, we analyzed by real-time PCR, the mRNA expression of mMEIS1, a homeobox gene that is associated with cell proliferation in neuroblastoma cells, and Neurod1, a gene that regulates neuronal differentiation." (PMID 38272891, 2024). "Among other markers associated with neuroblastoma aggressiveness in our series, NEUROD1 was already shown to promote cell growth in vitro and tumor formation in vivo in neuroblastoma cells." (PMID 36121500, 2022). "The researchers concluded that NeuroD1 expression is associated with increased tumorigenesis of neuroblastoma and associated with a poor prognosis in mouse models." (PMID 36230740, 2022). "Knockdown experiments using shRNA directed against NeuroD1 inhibited the motility of neuroblastoma cells which was associated with induction of Slit2 expression." (PMID 30760980, 2019). "We assessed the expression levels of NeuroD1 in common pancreatic cancer cell lines and in the human neuroblastoma cell line CHP134 via RT-qPCR." (PMID 41225636, 2025). "For example, NEUROD1 promotes neuroblastoma progression and is mediated by LINC00839/miR-454-3p axis." (PMID 36313290, 2022). "NeuroD1 has been shown to play an important role in the tumorigenesis of various peripheral tumors such as schwannomas and neuroblastomas." (PMID 36230740, 2022). "NEUROD1 seems to act mainly through ALK to favor neuroblastoma cell proliferation, directly binding to the promoter region of this gene." (PMID 36121500, 2022). "NeuroD1 promoted the proliferation of neuroblastoma cells in vitro and in vivo." (PMID 41673639, 2026). "High expression of NeuroD1 can promote neuroblastoma formation." (PMID 38134213, 2023). "Moreover, the authors noted that inhibition of NeuroD1 via short hairpin RNA (shRNA) resulted in decreased neuroblastoma cellular motility." (PMID 36230740, 2022). "In conclusion, we identify a strong prognostic impact of neuroendocrine-lineage transcriptional profiles in neuroblastoma, and suggest that the evaluation of NOTCH1, INSM1, YAP1, and NEUROD1 might help to further characterize the risk of relapse in neuroblastoma patients." (PMID 36121500, 2022). "Gene expression analysis of NSs by quantitative polymerase chain reaction (qPCR) of β-catenin, NeuroD1, SOX2, Nestin, β-tubulin 3, and DCX genes was compared between each group and the SHSY-5Y neuroblastoma (positive control for neuronal cells)." (PMID 36835256, 2023). "In a study assessing the impact of NeuroD1 in neuroblastoma, researchers examined the expression profile of NeuroD1 in MYCN-overexpressing transgenic mice and the role of NeuroD1 in tumor formation." (PMID 36230740, 2022).
ischemic stroke (9 papers, 2020 to 2026). A stroke disorder caused by obstruction of blood flow to the brain, due to thrombotic (local blood clot formation) or embolic (due to a blood clot or other material traveling from another site) event. "Together, these results demonstrate that NeuroD1 intravenous gene therapy attenuates ischemic brain injury and rescues neuronal loss after ischemic stroke." (PMID 38270116, 2023). "Together, these results suggest that intravenous NeuroD1 gene therapy can improve functional recovery after ischemic stroke as early as 7 days post-ischemic stroke." (PMID 38270116, 2023). "We next investigated the impact of the intravenous delivery of NeuroD1 on astrocytes response after ischemic stroke." (PMID 38270116, 2023). "Two months post-virus injection, immunostaining revealed that NeuroD1-GFP-infected cells co-stained with mCherry and NeuN, indicating that NeuroD1 can convert mCherry-labeled astrocytes into neurons after ischemic stroke." (PMID 38270116, 2023). "In this study, we tested the transduction profiles of AAV-PHP.eB and developed intravenous NeuroD1 gene therapy to treat ischemic stroke in mice." (PMID 38270116, 2023). "We further want to understand the impact of NeuroD1 on the global gene expression profile related with recovery of ischemic stroke." (PMID 38270116, 2023). "Together, these results suggest that NeuroD1-based intravenous gene therapy attenuates neuroinflammation and inhibits neuronal apoptosis after ischemic stroke." (PMID 38270116, 2023). "The most significantly enriched pathway revealed through KEGG enrichment analysis was the ECM-receptor interaction pathway, highlighting a role of NeuroD1 in modulating recovery progress after ischemic stroke." (PMID 38270116, 2023). "Recently, the same group further delivered the AAV-packaged NeuroD1 vector into astrocytes in the injured area in an ischemic stroke model of the primate macaque brain and successfully converted them into neurons." (PMID 35663583, 2022). "This study demonstrated that in situ NeuroD1-mediated AtN conversion therapy had a broad time window from 10 to 30 days following ischemic stroke." (PMID 34124038, 2021). "Following ischemic stroke in monkey cortex, the NeuroD1-mediated astrocyte-to-neuron (AtN) conversion significantly increased local neuronal density, reduced microglia and macrophage, and surprisingly protected parvalbumin interneurons in the converted areas." (PMID 33224952, 2020). "In this study, we demonstrate that ectopic expression of a single neural transcription factor NeuroD1 in the reactive astrocytes of monkey cortex after ischemic stroke can successfully convert astrocytes into neurons." (PMID 33224952, 2020). "Another pilot study using the non‐primate ischemic stroke models has proven that NEUROD1 is able to convert reactive astrocytes to neurons from 10 to 30 days following the onset, suggesting that in vivo AtN conversion may have a broad therapeutic time window." (PMID 40401537, 2025). "While more experiments are necessary to test the optimal time window, our results suggest that NeuroD1 AAV-based gene therapy may have a broad treatment window ranging from 10 to 30 days post ischemic stroke to have effective therapeutic intervention." (PMID 33224952, 2020). "Furthermore, the NeuroD1 gene therapy showed a broad time window in AtN conversion, from 10 to 30 days following ischemic stroke." (PMID 33224952, 2020). "Interestingly, most of the top 10 upregulated DEGs, such as Thbs1, CD36, ITGA4, and ADAMTS12, are involved in the function of endothelial cells, as shown in the heatmap, implying a role of NeuroD1 in regulating the gene expression of endothelial cells post ischemic stroke." (PMID 38270116, 2023). "Following the changes of signaling pathways in endothelial cells, NeuroD1 effectively protected BBB integrity, attenuated neuroinflammation, inhibited neuron apoptosis and rescued motor deficits after ischemic stroke." (PMID 38270116, 2023).
ischemic stroke (continued). "Together, these results indicate that NeuroD1 treatment protects BBB integrity and attenuates BBB leakage post ischemic stroke." (PMID 38270116, 2023). "Together, these results suggest that intravenous NeuroD1 delivery regulates AAV-PHP.eB transduction and recovery progress after ischemic stroke highly through modulating endothelial gene expression." (PMID 38270116, 2023). "In this study, we report an in vivo neural regeneration approach through AAV NeuroD1-based gene therapy to repair damaged brains after ischemic stroke in adult non-human primates (NHPs)." (PMID 33224952, 2020).